BRCA1 (BRCA1 DNA repair associated)
Diseases named in the same sentence as BRCA1 in open-access papers (continued):
Sharing a sentence is not in itself a finding about the gene and the disease.
tumor (continued). "Women with BRCA1 mutations are diagnosed at a younger age than noncarriers, and most tumours in the mutation carriers are of serous histology." (PMID 15477862, 2004). "BRCA1 protein is postulated to function as a tumour suppressor." (PMID 12698194, 2003). "It has to be considered that the preclinical study involves BRCA1 conditional knockout mice, a clearly different situation as compared to human tumour cells, which might result from a different carcinogenetic process." (PMID 12698198, 2003). "Half of the tumours (4/8) showed a physical deletion of the BRCA1 gene by FISH." (PMID 11710835, 2001). "Losses of BRCA1 markers correlated with larger tumour size, higher grade, and PgR expression." (PMID 8630282, 1996). "However, two cases showed AI distal to BRCA1, supporting the presence of a second tumour-suppressor gene on 17q." (PMID 8605099, 1996). "Genes such as BRCA1, CHEK2, and IKBKE are significantly upregulated in tumor tissues and serve as prognostic risk factors for GBM patients, suggesting that these genes may promote the initiation and progression of GBM by promoting neoplastic cell multiplication and impeding programed cell death." (PMID 41497799, 2025). "In keeping with low U-ssDNA accumulation in BRCA1-deficient cells, AP sites were also not significantly increased in cisplatin or HU-treated BRCA1-deficient cells (BRCA1 targeted by two different siRNAs) or in BRCA1 mutant tumor line UWB1.289." (PMID 41162355, 2025). "However, questions remain about how BRCA1 regulates R-loops genome-wide, the specific regions where BRCA1 processes R-loops, and the correlation between BRCA1's R-loop regulation function and tumor formation." (PMID 40271193, 2025). "Additionally, BRCA1 regulates the G2/M phase checkpoint of the cell cycle, and its overexpression may disrupt cell cycle control, enabling tumor cells to bypass cell cycle arrest and continue to proliferate." (PMID 41497799, 2025). "There are no studies investigating how somatic inactivation of BRCA1 would be related to increased MMP9 expression; however, a hypothetical explanation would be that genomic instability resulting from BRCA1 inactivation may induce an inflammatory response within the tumor microenvironment." (PMID 40870889, 2025). "Furthermore, HRD could be detected in various tumor entities harboring deleterious alterations in homologous recombination repair (HRR) genes other than BRCA1/2." (PMID 40278800, 2025). "At the beginning of the systemic therapy after tumor progression during ET plus CDK4/6i treatment, patient age, the number of metastatic sites, the presence of visceral involvement, and the type of treatment (ET vs CT based) were similarly distributed in BRCA1/2 mutated vs wild-type groups." (PMID 39982725, 2025). "Additionally, the homologous recombination deficiency (HRD) scoring system, which integrates the assessment of BRCA1/2 mutations, loss of heterozygosity (LOH), and tumor mutational burden (TMB), has further expanded the population eligible for PARP inhibitor therapy." (PMID 40395324, 2025). "Importantly, subgroup analyses stratified by BRCA mutation type (BRCA1 vs. BRCA2) and tumor biology (triple-negative vs. hormone receptor-positive) confirmed these findings, supporting the applicability of BCS across biologically distinct subgroups within the BRCA-mutated population." (PMID 41302125, 2025). "ADAR1 depletion in BRCA1-mutant cells causes an increase in R-loops and consequently, an upregulation of cytosolic nucleic acid sensing pattern recognition receptors (PRR), events which are associated with a tumor cell-autonomous type I interferon and integrated stress response." (PMID 40730818, 2025). "BRCA1 is a well-known tumor suppressor that plays a critical role in many important biological processes, including DNA damage repair, the cell cycle, centrosome amplification, DNA replication, chromatin remodeling, protein ubiquitination, and the tumor microenvironment." (PMID 40157910, 2025).
tumor (continued). "For instance, our analysis may exhibit bias as patients in non-EUR gAncestry populations tended to present with higher tumour grade (potentially due to increased ER- and/or enrichment of BRCA1/2 mutations), which is associated with decreased overall survival." (PMID 40394000, 2025). "The prevalence of BRCA1/2 germline pathogenic variants varies among ethnic groups and geographical areas; however, most BRCA1/2 germline pathogenic variant patients are young (<45 years of age), have aggressive disease characteristics, and have a family history of BRCA-related tumours." (PMID 40626017, 2025). "Consequently, the apparent differences in treatment outcomes between BRCA1 and BRCA2 carriers may be driven more by tumor phenotype than by the specific gene mutation itself." (PMID 41463210, 2025). "This explains the nature of post-NACT residual tumor masses: while short-term platinum therapy does not cause restoration of BRCA1/2 open reading frame via a second mutation, the selection of pre-existing BRCA1/2-proficient tumor cells is observed at significant frequencies." (PMID 40547808, 2025). "In humans, mutations in the BRCA1 and BRCA2 genes are strongly associated with an increased risk of breast, ovarian, prostate, pancreatic, melanoma, and peritoneal cancers, highlighting their essential role in DNA repair mechanisms, cell cycle control, and tumor suppression." (PMID 40004231, 2025). "Furthermore, BRCA1, beyond its established role in DNA repair, may affect immune surveillance mechanisms and the tumor’s ability to evade immune recognition through its involvement in maintaining genomic stability." (PMID 40708839, 2025). "Interestingly, higher cytoplasmic ADAR1p150 expression was also associated with increased tumor-infiltrating lymphocytes, regardless of the BRCA1 gene status." (PMID 40730818, 2025). "Similarly, homologous recombination deficiency (HRD), often caused by BRCA1 or BRCA2 loss, can promote tumor-intrinsic inflammation via STING and interferon (IFN) signaling and upregulate chemokines such as CCL5 and CXCL9, thereby enhancing immunogenicity and T cell inflammation." (PMID 41279139, 2025). "In addition, whether BRCA1-related biomarkers modify the well-established prognostic value of stromal tumor-infiltrating lymphocytes (sTILs) is unknown." (PMID 38191387, 2024). "In a second study assessing BRCA1 epimutations in WBC and matched tumor samples from TNBC, our results indicated such epimutations to be the underlying cause of around 20% of TNBC, far exceeding the percentage of cases carrying BRCA1 germline pathogenic genetic variants." (PMID 40225940, 2024). "Furthermore, ASHRA could quantitatively measure the HR activity in xenograft tumor tissues with HR activity that was gradually suppressed by inducible BRCA1 knockdown." (PMID 38589490, 2024). "Individually, the loss of either Wwox or Brca1 in the K14-Cre model may not be sufficient to initiate tumor formation." (PMID 38499540, 2024).
tumor (continued). "Interestingly, many of these USP4 loss-of-function mutations, including L301R, S315C and R559W, are found mainly located in the catalytic domain of USP4, suggesting that the DUB activity is critical for maintaining BRCA1 stability and hence its tumor suppression function." (PMID 38734703, 2024). "However, it was intriguing to find out that overexpression of BRCA1 could be observed in lungs of 4T1 derived tumor-bearing mice which suggests distant metastasis of the neoplastic cells." (PMID 38796426, 2024). "Notably, atypical tumour phenotypes appear in approximately 15% of non-BRCA1/2 MINAS." (PMID 39021548, 2024). "It depicts the state in which an HRR defect occurs in a tumor without a germline BRCA1/2 mutation." (PMID 38433576, 2024). "One hypothesis for the loss of BRCA1 methylation following chemotherapy is the substitutive expansion of a non-methylated subclone from a heterogeneous tumor cell population." (PMID 39769312, 2024). "Our previous study has shown that patients without tumor BRCA1 mutation and high sTILs may have the potential to forgo chemotherapy." (PMID 38191387, 2024). "Therefore, by utilizing littermate controls, we investigated whether treatment with Lipitor would restore NKT cell number and function in Brca-1 mutant mice and if it would have an effect on tumor development." (PMID 39596374, 2024). "Moreover, HR deficiency has been shown to identify TNBC tumours, including those without BRCA1/2 mutations that are more likely to respond to platinum-containing therapy." (PMID 39190283, 2024). "Therefore, we hypothesize that CaSR may affect the cisplatin resistance of tumor cells through its effects on cyclin B1 and BRCA1." (PMID 39113697, 2024). "However, several notable tumor suppressors of modest size, including BRCA1, NF1, and RB1, could be phased completely in only around half of tumors, suggesting other locus-related features may reduce their phasing potential." (PMID 39406235, 2024). "Interestingly, we found that tumor BRCA1-PM may modify the association between sTILs and OS, as shown by a nearly two-fold increase in OS for tumor BRCA1-PM patients with every 10% increment of sTILs, compared to those with other BRCA1 status." (PMID 38191387, 2024). "Thus, we hypothesised that tumours with CRS3 were more likely to have a germline BRCA1/2 PV compared to tumours with germline BRCA1/2 wild type." (PMID 39550490, 2024). "During meiosis, the tumor suppressor BRCA1/BRC-1 and structural maintenance of chromosomes 5/6 (SMC-5/6) complex genetically interact to promote high fidelity DNA double strand break (DSB) repair, but the specific DSB repair outcomes these proteins regulate remain unknown." (PMID 39115289, 2024). "According to these results, the patients with somatic mutations in BRCA1/2, detected in this study, could benefit from PARPi targeted therapy, since most cases are HGSOC present 100% representativeness in the tumor and, therefore, low levels of contamination by normal cells." (PMID 38308422, 2024). "Moreover, two out of three of the FFPE samples had a GIS reported, suggesting that the quality and quantity of tumour DNA extracted reached the required threshold for full assay completion (the GIS for the two tumours with a BRCA1 Exon 13 duplication were 68 and 70)." (PMID 38201604, 2023). "One patient had a BRCA1 mutation detected in their tumour, however as a germline sample was not available, we were not able to determine whether this was a germline or somatic mutation, and a clinical germline testing result was not available." (PMID 38072854, 2023). "Finally, the ‘other’ category provided informative evidence towards variant pathogenicity for both BRCA1 (LR: 3.62 (95% CI: 2.61–5.03), supporting evidence) and BRCA2 (LR: 3.46 (95% CI: 2.20–5.43), supporting evidence), if tumours were undifferentiated or poorly differentiated." (PMID 37076566, 2023). "BRCA1 gene methylation may also play a crucial role in tumor development." (PMID 37759912, 2023).
tumor (continued). "The increased sensitivity to these drugs in tumor cells with either somatic or germline BRCA1 mutations suggests that the mechanism of HRD does not depend on whether the BRCA1 mutation was inherited, or arose during the life of the patient." (PMID 36902416, 2023). "It has been suggested that ex vivo culture may select against BRCA1/2-mutant tumours." (PMID 37592171, 2023). "While low patient numbers preclude correlations between HRD and efficacy, germline BRCA1/2 mutation detection from tumor-only sequencing shows high sensitivity and non-BRCA genetic/genomic events do not appear to influence talazoparib sensitivity in the ABRAZO trial." (PMID 37803017, 2023). "The somatic NAHR burden did not vary by tumor type nor was it lower in tumors harboring biallelic pathogenic mutations in DNA repair genes, including frequently mutated homologous recombination pathway mediators (BRCA1, BRCA2, PALB2 and RAD51C)." (PMID 37945902, 2023). "A phase 1 trial has evaluated the combination of olaparib with cediranib in pretreated TNBC patients with or without BRCA1/2 mutation; however, the trial observed limited anti-tumor activity (no objective response and 2 SD in 8 patients), likely due to the small sample size." (PMID 37775744, 2023). "Our study shows that if germline BRCA1/2 testing is only performed for patients with a positive tumour BRCA1/2 test result, and tumour testing is performed using Myriad’s myChoice® companion diagnostic, a proportion of germline BRCA1/2 large rearrangements could be missed." (PMID 38201604, 2023). "It is also important to note that no tumour BRCA1/2 test has been validated to distinguish between germline and somatic pathogenic variants, so all patients with a tumour BRCA1/2 pathogenic variant, irrespective of the tumour test used, should undergo germline testing." (PMID 38201604, 2023). "For example, tumours with NTRK fusion may be treated with a larotrectinib; olaparib treatment targets a mutation in the BRCA1 or BRCA2 gene, and pembrolizumab is approved by FDA only in the cancers with MSI-H (microsatellite instability high) or MMR-D (mismatch repair deficiency)." (PMID 36765737, 2023). "We noted for non-BRCA1/BRCA2 tumours, only a small proportion displayed high HRDetect scores and were characterized by concomitant promoter hypermethylation or in one case a RAD51D splice variant previously reported as having unknown significance to potentially explain their BRCAness." (PMID 37316882, 2023). "Many of the most frequent actionable alterations within TMB-H tumors were within tumor suppressor pathways (PIK3CA/PTEN, CDKN2A, BRCA1/2, NF1, ATM, and TSC1/2), suggesting that many variants may be passenger rather than driver alterations in the setting of highly altered tumors." (PMID 36602798, 2023). "Finally, we investigated the prevalence of germline pathogenic variants in non-BRCA1/2 HRR-associated genes in women diagnosed with non-mucinous high-grade EOC aged ≥80 who also underwent tumour testing using Myriad’s myChoice® CDx." (PMID 36765687, 2023). "Tumors with the loss of heterozygosity in either the BRCA1 or 2 gene correspondingly show defects in repairing double-strand DNA breaks, and are sensitive to inhibitors of PARP1, an enzyme that contributes to repairing single-strand DNA breaks, by causing the synthetic lethality of tumor cells." (PMID 37664647, 2023). "Nevertheless, 20% of BRCA1/2-mutated ovarian malignancies do not respond to PARPi, highlighting the urgent need for new treatment approaches for inherently or acquired resistant tumours." (PMID 35964058, 2022).
tumor (continued). "We found that the mRNA levels of S100a8/S100a9 were increased in MTMG tissues at multiple developmental stages and tumor tissues, S100a9 expression was increased dramatically in luminal and stromal subpopulations, and Brca1-MT mammary epithelial cell line (G600)." (PMID 35304461, 2022). "Moreover, while both BRCA1 and BRCA2 associated tumours have a homologous recombination repair deficiency, there are phenotypical characteristics which could lead to a different chemotherapeutic response." (PMID 34929424, 2022). "Taken together, these results are consistent with the explanation that the loss of methylation in BRCA1meth tumors is the result of demethylation of one BRCA1 promoter allele in most of the cells in the bulk tumor, and not through the expansion of a non-methylated subclone." (PMID 35857626, 2022). "Interestingly, in BRCA1-deficient ovarian cancer models, PARP inhibition with olaparib increased CD4+ and CD8+ T cells in the tumor and in circulation, reduced their expression of inhibitory receptors PD-1, Tim-3, and Lag-3, and increased their levels of TNF-alpha and IFN-γ secretion." (PMID 36276148, 2022). "Moreover, TNBC is an immunogenic tumor, however, BRCA1 mutation status has not yet been proven as predictive marker for immune checkpoint inhibition." (PMID 35715861, 2022). "Lastly, for deceased patients with HGSC who did not undergo BRCA1/2 genetic testing, testing of archived tumour tissue to detect possible germline HCP variants could provide essential information to family members." (PMID 36011309, 2022). "Moreover, the transcriptional mechanism of Brca1 is well defined in tumor cells." (PMID 36430332, 2022). "Moreover, we also found reduced expression of ATP11b in Brca1-MT mammary glands compared with WT glands, and it was even lower in tumor tissues, suggesting that Brca1 might play a role in maintaining ATP11b expression." (PMID 35025764, 2022). "Although as one might expect, more mutations were detected in the tumor tissue, including MTOR and BRCA1; however, the pathogenic PDGFRA variant (c.1939A > G, p.Ile647Val) was found in the urinary exosomes from both UC and NanoPoms preparations, but not in the tumor tissue cells." (PMID 35787656, 2022). "This explanation could be valid for the three tumors with BRCA1 promoter methylation and the tumor with a somatic BRCA2 mutation with LOH, which were not identified as HRD by BRCA1/2-like classifier and both BRCA1/2-like classifier and CHORD, respectively." (PMID 35662281, 2022). "In TNBC patients without a germline BRCA1/2 mutation, a significant number of tumours harbor HRD." (PMID 35124703, 2022). "We speculate that these observations might indicate that loss of BRCA1 leads to more EMT-like features in a proportion of cells within a tumor, but not the extent that the intrinsic subtype of the tumor bulk is significantly changed." (PMID 35236825, 2022). "Indeed, talazoparib has been shown to induce considerable in vitro cytotoxicity regardless of BRCA1 mutation status, although it is still more potent in BRCA1 mutant tumor cells." (PMID 35641483, 2022). "Alternatively, changes in pathways that compensate for the loss of Polθ activity could conceivably cause resistance, as could molecular changes that compensate for dysfunction in the tumour suppressor being synthetic lethal targeted by a Polθi (e.g. BRCA1, BRCA2)." (PMID 35567571, 2022). "Moreover, after cisplatin treatment, the MCF7-H and MCF7-J cybrids showed 3.15-fold and 2.78-fold increase in BRCA1 transcription, respectively, which may contribute to the inhibition of tumor growth from the treatment." (PMID 35743133, 2022). "Given that data on the prognostic value of tumor size in BRCA1/2 mutation carriers are currently lacking, the purpose of the current study is to determine the prognostic value of this tumor characteristic within a population of BRCA1/2 mutation carriers." (PMID 35507134, 2022).